PTGES3 (prostaglandin E synthase 3)
Diseases named in the same sentence as PTGES3 in open-access papers (continued):
Sharing a sentence is not in itself a finding about the gene and the disease.
tumor (continued). "Our findings define a non-canonical nuclear function for PTGES3, identifying it as a critical molecular switch that couples tumor aggressiveness with microenvironmental remodeling, thus presenting a promising therapeutic target for HCC." (PMID 41880053, 2026). "Interestingly, we also note the downregulation of PTGES3, a gene theoretically involved in supporting tumorigenesis, suggesting a paradoxical molecular signature that may reflect complex regulatory feedback, context-dependent tumor behavior or tissue heterogeneity." (PMID 40950184, 2025). "In addition, some SNO proteins can participate in the proliferation, metastasis, and apoptosis of CRC by regulating the tumor endocrine and metabolic pathways, such as PKM, GAPDH, LDHA, GLUD1, and PTGES3." (PMID 37124724, 2023). "Principle component analysis (PCA) was used to reduce the dimensionality of the TCGA-COAD and READ data sets for the tumor and normal samples, as well as for sigmoid and transverse normal colon samples, based on the expression of PTGS1, PTGS2, PTGES3, and TERT." (PMID 31614548, 2019). "It is reasonable to assume that in the present tumor both MDM2 amplification and the fusion genes PTGES3-PTPRB, HMGA2-DYRK2, TMBIM4-MSRB3 and USP15-CNTN1 are located on the ring chromosome although lack of suitable material prevented us from determining this with certainty." (PMID 25176350, 2014). "Increasing studies have shown that PTGES3 plays a nonnegligible role in tumor development." (PMID 37274225, 2023). "In addition, we found that PTGES3 was negatively correlated with stromal, immune, and ESTIMATE scores and found that upregulation of PTGES3 was correlated with low infiltration of immune and stromal cells but high tumor purity in LUAD." (PMID 37416927, 2023). "Because MDM2 amplification and the fusion transcripts PTGES3-PTPRB, HMGA2-DYRK2 and TMBIM4-MSRB3 were found both in the primary tumor and in the metastasis, they are components of the same clone and may be involved both in initiation and progression of the tumor." (PMID 25176350, 2014). "Although Prostaglandin E Synthase 3 (PTGES3) functions canonically as a cytoplasmic Heat Shock Protein 90 (HSP90) co-chaperone, its non-canonical nuclear role in orchestrating tumor-immune crosstalk remains undefined." (PMID 41880053, 2026). "In contrast, genes such as PTGES3 and UBTF exhibited significant negative correlations, suggesting tumor-cell-intrinsic functions." (PMID 40299459, 2025).
cancer (11 papers, 2015 to 2025). A tumor composed of atypical neoplastic, often pleomorphic cells that invade other tissues. "It showed that PTGES3 methylation was strongly associated with PTGES3 expression in most cancer types except GBM, PRAD, LIHC, KICH, LAML, CHOL, and UCEC." (PMID 37274225, 2023). "The survival association for pan-cancer was processed to explore the association between PTGES3 expression level and prognosis of cancer patients." (PMID 37274225, 2023). "Our results suggested that higher PTGES3 expression could be associated with malignant tumor development and worse prognosis in HCC patients." (PMID 37274225, 2023). "Therefore, we performed a comprehensive analysis of the association between PTGES3 expression and prognosis in 33 types of cancer via databases covering TCGA, LinkedOmics, GDSC, and TIMER." (PMID 37274225, 2023). "Chaitanya demonstrated that Gedunin can bind to the surface of PTGES3 and promote cancer cell apoptosis." (PMID 38245717, 2024). "Using the GSCA database, we obtained the relationship between drug IC50 and PTGES3 expression in the GDSC database in pan-cancer." (PMID 37274225, 2023). "Consistent with the results of previous studies, our study revealed that PTGES3 was abnormally expressed in many cancers." (PMID 37416927, 2023). "According to our study, significant differences in PTGES3 expression level were found with 14 types of cancer." (PMID 37274225, 2023). "We first analyzed PTGES3 expression in pan-cancer to determine the function of PTGES3 in carcinogenesis." (PMID 37274225, 2023). "In a wide range of cancer, our investigation found that PTGES3 expression has substantial relationships with the infiltration degree of CD4+ T cells and MDSCs." (PMID 37274225, 2023). "Another group of chaperone genes, such as CCT6A, CCT4, TCP1, CCT5, PTGES3 and CCT7, were previously implicated in cancer cell proliferation and predicts poor prognosis in HCC36,37." (PMID 33431814, 2021). "PTGES3 is upregulated in multiple cancer types and promotes tumorigenesis and progression." (PMID 37416927, 2023). "We also explored the PTGES3 methylation landscape in pan-cancer." (PMID 37274225, 2023). "PTGES3 has been reported to reduce geldanamycin sensitivity in mammalian cancer cells." (PMID 37416927, 2023). "Furthermore, the prognostic value of PTGES3 in LUAD was evaluated through TCGA, GEPIA2, and KM Plotter databases, which demonstrated that the upregulation of PTGES3 in cancer tissues was correlated with poor OS and DSS." (PMID 37416927, 2023). "PTGES3 was also associated with a positive or negative prognosis in a variety of cancers, which was mainly associated with DNA methylation, CNV, MSI, TMB, andmismatch repair-related genes." (PMID 37274225, 2023). "However, the role played by PTGES3 in cancer has only been reported in a few studies, and for only a few types of cancer." (PMID 37274225, 2023). "Our study revealed that PTGES3 expression level was upregulated in most cancers." (PMID 37274225, 2023). "A few studies have reported the promising role of PTGES3 in cancer immunity." (PMID 37416927, 2023). "Our results indicated that PTGES3 expression might have a prognostic value in a wide range of cancer, especially LIHC, ESCA, MESO, and LUAD." (PMID 37274225, 2023). "There has been a recent increase in studies focusing PTGES3 expression in several cancer types." (PMID 37416927, 2023). "The PTGES3′s protein partner subset is enriched with pathway terms such as “protein processing in endoplasmic reticulum”, “pathways in cancer” (KEGG); “cellular responses to external stimuli”, “aryl hydrocarbon receptor signaling” and “TNF alpha Signaling Pathway” (Reactome)." (PMID 35453789, 2022). "Even though the altered expression of many genes is maintained or even exacerbated in tumors, a subset overturns its deregulation, reversing the expression levels in the cancer tissue to either upregulation (i.e., PTGES3) or a strong downregulation (i.e., PTGIS)." (PMID 26207152, 2015).
cancer (continued). "Therefore, PTGES3 was suggested as a cancer-promoting biomarker in HCC." (PMID 37274225, 2023). "For this reason, the increase in cPGES/PTGES3 expression in GBM can be considered cancer-specific, just like mPGES-1/PTGES, which has increased expression in eight types of cancer and decreased in three." (PMID 36765904, 2023). "Our study indicated that PTGES3 expression has influenced TMB in 12 types of cancer and MSI in 10 types of cancer, which affected the response to immune checkpoint inhibitory therapy." (PMID 37274225, 2023). "In particular, the TERT branch is affected by p21 (PTGES3) in LS-CRC, while in s-CRC cancers, we observe high influence of heat shock proteins (HSP90AB1 and HSPA1A)." (PMID 31750255, 2019). "Notably, analysis of PTGES3 gene essentiality upon Cas9 knockout across 1,070 diverse cancer cell lines present in the Cancer Dependency Map53 demonstrated that PTGES3 is not classified as a commonly essential gene." (PMID 41193657, 2025). "Therefore, we speculate that PTGES3 and HNRNPC could synergistically promote cancer occurrence and development, which needs to be explored further." (PMID 37416927, 2023). "No bioinformatic analysis of PTGES3 in pan-cancer has been performed yet." (PMID 37274225, 2023). "However, analysis of PTGES3 in pan-cancer has not been performed yet." (PMID 37274225, 2023). "However, biological information analysis for PTGES3 in pan-cancer has not been performed yet." (PMID 37274225, 2023).
PTGES3 also shares sentences with these, for which no sentence is quoted: lung carcinoma (4 papers); breast carcinoma (2); infection (2); acute lymphoblastic leukemia (1); Alzheimer disease (1); Arthritis (1); bladder urothelial carcinoma (1); brain cancer (1); Co-infection (1); colon adenocarcinoma (1); colon cancer (1); colorectal tumors (1); diffuse large B-cell lymphoma (1); esophageal carcinoma (1); gallbladder adenocarcinoma (1); genitourinary cancer (1); head and neck squamous cell carcinoma (1); legionellosis (1); liver cancer (1); lung squamous cell carcinoma (1); lymphoma (1); prostate adenocarcinoma (1); rectum adenocarcinoma (1); SARS-CoV Infections (1); uterine corpus endometrial carcinoma (1).